LARS1 (leucyl-tRNA synthetase 1)
Description:
Aminoacyl-tRNA synthetase that catalyzes the specific attachment of leucine to its cognate tRNA (tRNA(Leu)). It performs tRNA aminoacylation in a two-step reaction: Leu is initially activated by ATP to form a leucyl-adenylate (Leu-AMP) intermediate; then the leucyl moiety is transferred to the acceptor 3' end of the tRNA to yield leucyl-tRNA. To improve the fidelity of catalytic reactions, it is also able to hydrolyze misactivated aminoacyl-adenylate intermediates (pre-transfer editing) and mischarged aminoacyl-tRNAs (post-transfer editing).
Synonyms: LeuRS; cLRS; LARS; HSPC192; FLJ10595; FLJ21788; LEUS; RNTLS; ILFS1; LFIS; LRS; PIG44; hr025Cl
Tractability: Small molecule: a structure with a bound ligand is known; a high-quality ligand is known; it has a binding pocket of medium quality; it belongs to a druggable protein family. PROTAC: ubiquitination databases record sites on it; a small molecule that binds it is known.
Target class: Enzyme; Ligase
Gene: Protein-coding gene on chromosome 5 (146,110,566 to 146,182,696, reverse strand). Ensembl gene ENSG00000133706.
Subcellular location: Cytoplasm
Subcellular location (Human Protein Atlas): Cytosol; Nuclear bodies
Pathways (Reactome):
Developmental Biology: Transcriptional and post-translational regulation of MITF-M expression and activity
Metabolism: Selenoamino acid metabolism
Metabolism of proteins: Cytosolic tRNA aminoacylation
Gene Ontology:
Molecular function: aminoacyl-tRNA deacylase activity; glutamine-tRNA ligase activity; GTPase activator activity; leucine-tRNA ligase activity; protein binding; aminoacyl-tRNA ligase activity; ATP binding; nucleotide binding
Biological process: cellular response to amino acid starvation; cellular response to amino acid stimulus; cellular response to L-leucine; cellular response to leucine starvation; glutaminyl-tRNA aminoacylation; leucyl-tRNA aminoacylation; positive regulation of TORC1 signaling; tRNA aminoacylation for protein translation; aminoacyl-tRNA metabolism involved in translational fidelity
Cellular component: aminoacyl-tRNA synthetase multienzyme complex; cytoplasm; cytosol; endomembrane system; endoplasmic reticulum; lysosome
Genetic constraint (gnomAD): Loss-of-function variants: 65 observed, 101.49 expected, observed/expected ratio (o/e) 0.64, 90% interval 0.52 to 0.79. The upper end of that interval is the gene's LOEUF score, 0.79, which puts it in group 3 of 6, group 1 being the genes least tolerant of losing a copy. Missense variants: 851 observed, 990.88 expected, observed/expected ratio (o/e) 0.86, 90% interval 0.81 to 0.91. Synonymous variants: 310 observed, 339.22 expected, observed/expected ratio (o/e) 0.91, 90% interval 0.83 to 1.
Homologues: Orthologues: chimpanzee LARS1 (99% identical), macaque LARS1 (99% identical), dog LARS1 (95% identical), guinea pig LARS1 (93% identical), rabbit LARS1 (92% identical), pig LARS1 (91% identical), mouse Lars1 (90% identical), rat Lars1 (90% identical), tropical clawed frog lars1 (84% identical), Drosophila melanogaster LeuRS (60% identical), Caenorhabditis elegans lars-1 (57% identical), zebrafish lars1b (54% identical), and 1 more. Paralogues in human: IARS1 (16% identical), VARS2 (16% identical), VARS1 (15% identical), IARS2 (13% identical), LARS2 (12% identical), MARS1 (9% identical), MARS2 (7% identical).
Diseases named in the same sentence as LARS1 in open-access papers:
LARS1 is named in the same sentence as 61 diseases in open-access papers, as found by Europe PMC text mining. Sharing a sentence is not in itself a finding about the gene and the disease. The quoted sentences say what the papers report.
breast carcinoma (8 papers, 2019 to 2025). "In breast cancer, upregulated expression of specific tRNAs for glutamic acid drives a metastatic pathway, and leucyl-tRNA synthetase 1 (LARS1) was shown to function as a tumor suppressor by promoting codon-specific translation of growth suppressive genes." (PMID 39588782, 2024).
anemia (6 papers, 2013 to 2024). A reduction in the number of red blood cells, the amount of hemoglobin, and/or the volume of packed red blood cells. "LARS1- and MARS1-associated disorders are associated with neurological impairment, MRI abnormalities, liver disease, anemia, and endocrine abnormalities and show the greatest clinical overlap with the YARS1 p.(Arg367Trp)-associated phenotype delineated here." (PMID 34536092, 2021).
lung carcinoma (6 papers, 2020 to 2024). "A previous study demonstrated that knockdown of LARS1 inhibits cell migration and colony-forming ability in lung cancer." (PMID 36612155, 2022). "LARS was reported to be closely related to the growth and migration of lung cancer cells by observing the reduced migration and colony formation from LARS1 siRNA knockdown in a lung cancer cell line." (PMID 37096225, 2023).
acute liver failure (4 papers, 2016 to 2024). Rapid deterioration of liver function causing encephalopathy and coagulopathy. "The combination of protein domain and variant distribution data as well as pathogenicity score modeling was applied in two different subtypes of acute liver failure in infancy caused by variants in the genes TRMU and LARS1 encoding for tRNA processing enzymes." (PMID 36789265, 2023).
infantile liver failure syndrome type 1 (4 papers, 2021 to 2025). "Biallelic pathogenic variants of LARS1 cause infantile liver failure syndrome type 1 (ILFS1), which is characterized by acute hepatic failure with steatosis in infants." (PMID 38807157, 2024). "Mutations in LARS1 have been associated with infantile liver failure syndrome type 1 (ILFS1)." (PMID 37274208, 2023). "Infantile liver failure syndrome type 1 (ILFS1; OMIM 615438) is a rare autosomal recessive disorder caused by pathogenic variants of the LARS1 gene (OMIM 151350) located on chromosome 5q32, which encodes leucyl-tRNA synthetase (LARS) and catalyzes the ligation of leucine to leucine tRNA." (PMID 38807157, 2024).
osteosarcoma (3 papers, 2022 to 2024). A usually aggressive malignant bone-forming mesenchymal neoplasm, predominantly affecting adolescents and young adults. "CCK8 assay was used to detect the effect of essential gene-LARS (Leucyl-TRNA Synthetase 1) on the proliferation of osteosarcoma." (PMID 35962451, 2022).
clear cell renal cell carcinoma (1 paper, 2022). "In contrast, LARS1, NARS1, QARS1, and LARS2 are significantly underexpressed in acute myeloid leukemia, pancreatic adenocarcinoma, squamous cell lung carcinoma, and clear cell renal cell carcinoma, respectively." (PMID 35501376, 2022). "For instance, EPRS1, LARS1, MARS1, TARS2, and YARS2 show increased gene expression in pancreatic adenocarcinoma, clear cell renal cell carcinoma, prostate adenocarcinoma, diffuse large B cell lymphoma, and follicular variant of papillary thyroid carcinoma, respectively." (PMID 35501376, 2022).
colorectal cancer (1 paper, 2022). A primary or metastatic malignant neoplasm that affects the colon or rectum. "Further studies evaluating the clinical significance of the PGC-1α/LARS1/AKT/GSK-3β/β-catenin axis in human colorectal cancer patients and therapeutic potentials of several LARS1 inhibitors in PGC-1α-overexpressing colorectal cancer are needed." (PMID 36612155, 2022). "Our results showed that PGC-1α regulated cell proliferation and invasion by regulating the LARS1/AKT/GSK3β/β-catenin axis in human colorectal cancer cells." (PMID 36612155, 2022). "However, the molecular network of PGC-1α and LARS1 in human colorectal cancer cells remains unclear." (PMID 36612155, 2022). "First, we did not evaluate the in vivo effect of the PGC-1α/LARS1 axis on tumor progression of human colorectal cancer." (PMID 36612155, 2022). "Until now, the molecular network of PGC-1α and LARS1 in human colorectal cancer cells are not explored." (PMID 36612155, 2022). "To confirm whether PGC-1α regulates the expression levels of LARS1, p-AKT, p-GSK-3β, p-mTOR, p-S6K1, p-4EBP1, β-catenin, c-Myc, cyclin D1, and vimentin in other colorectal cancer HT-29 and SNU-C4 cells, we performed qRT-PCR and Western blot analysis." (PMID 36612155, 2022). "Altogether, these results implicate that PGC-1α regulates cell proliferation and invasion through modulation of the LARS1/AKT/GSK3β/β-catenin axis and that LARS1 might be a potential therapeutic target for PGC-1α-overexpressing human colorectal cancer as depicted in a schematic diagram." (PMID 36612155, 2022).
liver steatosis (1 paper, 2024). "Our findings suggest that dysregulation of autophagy, caused by biallelic pathogenic variants of LARS1 leads to liver steatosis." (PMID 38807157, 2024).
cancer (15 papers, 2016 to 2025). A tumor composed of atypical neoplastic, often pleomorphic cells that invade other tissues. "In addition, it was reported that inhibition of LARS1 may reduce cancer cell proliferation via the p21 signaling pathway and cause apoptosis." (PMID 36612155, 2022). "Mechanistically, MOTS‐c exerted anti‐cancer effects by attenuating USP7‐mediated deubiquitination of LARS1 and promoting LARS1 degradation." (PMID 39321430, 2024). "Although LARS1 has been shown to be a cancer‐promoting molecule in other tumors, its role in OC is unclear." (PMID 39321430, 2024). "A pan‐cancer analysis of LARS1 was performed using the TCGA database, which revealed that the mRNA levels of LARS1 were notably elevated in various tumors, including OC, compared to normal tissues." (PMID 39321430, 2024). "Several studies have shown the importance of LARS1 in mTORC1 activation in various cell types, especially in cancer cells." (PMID 37258576, 2023). "There are still controversies about the roles of peroxisome proliferator-activated receptor γ coactivator 1α (PGC-1α) and leucyl-tRNA synthetase 1 (LARS1) in cancer." (PMID 36612155, 2022). "The functional significance of LARS1 as a leucine sensor for mTORC1 activation in cancer has been further investigated in different cancer cell lines and in vivo models." (PMID 35501376, 2022). "In addition, LARS1 was shown to possess codon-specific tumor suppressive functions, which highlights the importance of this amino acid for cancer." (PMID 39588782, 2024). "Collectively, these findings indicate that LARS1 is a cancer‐promoting factor in OC." (PMID 39321430, 2024). "As the coupling effect of SNHG6 was investigated in cancer cells, cholesterol availability sensed by FAF2 was hypothesized to crosstalk with LARS1, which senses leucine availability, in turn activating mTORC1 for downstream signaling pathway activation in diseased states, such as cancer." (PMID 37258576, 2023). "Although the exact role of LARS1 phosphorylation at S720 in cancer is not fully understood, this work suggest that LARS1 modulates its leucine binding capability under metabolic stress in cancer, such as glucose starvation, thereby providing a metabolic adaptation and survival strategy." (PMID 35501376, 2022). "Mechanistically, MOTS‐c exerts anti‐cancer effects by attenuating USP7‐mediated deubiquitination of LARS1 and promoting LARS1 degradation." (PMID 39321430, 2024). "The mRNA and protein levels of LARS1 were significantly higher in the cancer than those in adjacent non-tumor tissues based on PCR and IHC." (PMID 41035672, 2025).
tumor (14 papers, 2018 to 2025). "We found that high LARS1 mainly associated with Myc targets v1, G2M checkpoint, E2F targets, Mitotic spindle, etc, related to the proliferation of tumor cells, dysregulation of the cell cycle, genomic instability, and drug resistance, indicating the occurrence and development of tumors." (PMID 41035672, 2025). "As to HCC, it is demonstrated that higher LARS1 expression level was observed in tumor tissues with poor prognosis and correlated with AFP, histologic grade, pathologic stage and so on." (PMID 41035672, 2025). "To investigate the relationship between LARS1 expression and the tumor immune microenvironment, we divided malignant cells into LARS1-high and LARS1-low groups and evaluated differences in immune infiltration." (PMID 41035672, 2025). "We further extracted LARS1 as the key gene of the model and found that high LARS1 tended to have poorer prognosis with higher expression in tumor tissues than in adjacent non-tumor ones in both TCGA and GEO." (PMID 41035672, 2025). "Furthermore, LARS1 expression was higher in tumor tissues than in adjacent non-tumor tissues, which was verified in different datasets of GEO." (PMID 41035672, 2025). "Together, upregulated LARS1 may play a tumor‐promoting role during OC progression." (PMID 39321430, 2024). "Thus, further research is warranted in the context of using in vivo models to evaluate whether modulation of LARS1 expression by LARS1 overexpression or LARS1 knockdown can reverse PGC-1α actions on tumor progression." (PMID 36612155, 2022). "Under hypoxia-induced tumor microenvironment, activated HIF-1α promotes the expression of leucyl-tRNA synthetase 1 (LARS1) in exosomes derived from PC cells." (PMID 41019994, 2025). "Single-cell transcriptomic analysis manifested the heterogeneity of LARS1 in HCC and suggested that it may contribute to tumor progression through modulation of amino acid metabolism." (PMID 41035672, 2025). "Moreover, we revealed the heterogeneous expression of LARS1 in HCC and its potential tumor-promoting mechanisms by single-cell transcriptomic analysis." (PMID 41035672, 2025). "We analyzed the discrepancy of LARS1 in tumor and adjacent non-tumor tissues in both TCGA and the Gene Expression Omnibus (GEO) database and the results were verified in HCC patients undergoing hepatectomy from our hospital via PCR and Immunohistochemistry (IHC)." (PMID 41035672, 2025). "Interestingly, LARS1 was not only highly expressed in malignant cells but also showed elevated expression in endothelial and fibroblast cells, suggesting that these non-malignant cells might also exhibit tumor-promoting activity." (PMID 41035672, 2025).
infection (3 papers, 2016 to 2025). The state of being infected such as from the introduction of a foreign agent such as serum, vaccine, antigenic substance or organism. "Quite the contrary, many clones targeting genes required for translation, including those encoding aminoacyl-tRNA synthetases (hars-1, lars-1, rars-1, tars-1, wars-1) and eIF subunits, were required for expression of nlp-29 after infection." (PMID 27129311, 2016). "Smaller cohorts have also shown potential benefits from isoleucine (IARS1) and leucine (LARS1) supplementation, with observed improvements in growth, liver function, and infection resistance." (PMID 41404429, 2025).
LARS1 also shares sentences with these, for which no sentence is quoted: liver failure (4 papers); Failure to thrive (3); Hypoalbuminemia (3); Liver dysfunction (3); cervical cancer (2); developmental delay (2); nervous system disorder (2); non-small cell lung carcinoma (2); renal carcinoma (2); Acute hepatic failure (1); breast tumor (1); Cognitive impairment (1); colon cancer (1); diabetic nephropathy (1); diffuse large B-cell lymphoma (1); genetic disease (1); gestational diabetes (1); hepatocellular carcinoma (1); Hypertension (1); immune dysfunction (1); infantile liver failure syndrome type 2 (1); Insulin resistance (1); intrauterine growth restriction (1); liver disease (1); lymph node metastasis (1); malaria (1); melanoma (1); MELAS syndrome (1); microcephaly (1); microcytic anemia (1).
A further 19 diseases each share a sentence with LARS1 in 1 paper.